SHH (sonic hedgehog signaling molecule)
Diseases named in the same sentence as SHH in open-access papers (continued):
Sharing a sentence is not in itself a finding about the gene and the disease.
cancer (continued). "As touched upon above, pancreatic tumor cells secrete SHH, a HH ligand, which recruits fibroblasts – characterized in this context as cancer-associated fibroblasts (CAFs) – to form the dense ‘desmoplastic’ or fibrotic stroma of that cancer type." (PMID 26839398, 2016). "Normalizing fibroblasts “pre activation” using appropriate pharmacological substances could improve the high susceptibility of NBCCS patients toward BCCs development and, presumably, of human cancers associated to unbalanced SHH/PATCHED pathway." (PMID 26694869, 2015). "Abnormal induction of SHH signaling through different means—e.g., down-regulation or mutation of SHH receptor(s) or effectors, autocrine, or paracrine expression of SHH—has been associated with many different types of human cancers." (PMID 23940460, 2013). "Aberrant activation of SHH signaling is implicated in many human cancers." (PMID 22087285, 2011). "Therefore, understanding the role of SHH dysregulation in SHH-mediated cancers and how the novel GLI1 splice variants may promote various phenotypes is paramount to further mechanistic discovery and drug development." (PMID 32957513, 2020). "Therefore, SHH signaling in the cancer parenchyma of OSCC may be involved in causing epithelial-to-mesenchymal transition and invasion, similar to other tumors." (PMID 31744214, 2019). "Cancer stem cells upregulate effectors in many key developmental signaling pathways such as Sonic Hedgehog (SHH), NOTCH and TGFβ, each of which has been associated with stem cell maintenance and activation of the epithelial mesenchymal transition (EMT) process by which cancer stem cells may arise." (PMID 29883385, 2018). "While several cancer-associated genes/proteins exhibited similar expression across the two cell lines, upregulation of a number of signature proteins and enrichment of key components of SHH and WNT signaling pathways were uniquely observed in Daoy and UW228, respectively." (PMID 28248256, 2017). "ZIC1 and ZIC4 are known to be regulators of the SHH signaling pathway by antagonizing the transcriptional activity of Gli proteins, and arefound to be silenced by hypermethylation in several types of cancers." (PMID 40952541, 2025). "SHH is critical in the activation of GBM cancer stem cells, and inhibition of the SHH signaling pathway eliminates GBM tumorigenicity while also increasing the sensitivity of GBM patients to radiotherapy and concomitant and adjuvant TMZ15,16." (PMID 40802352, 2025). "ROC1 overexpression leads to the ubiquitin-dependent degradation of SUFU, an inhibitor of Gli2, allowing Gli2 to activate the SHH pathway and promote cancer cell growth." (PMID 40635786, 2025). "As previously reported, GLI2 is a transcription factor, which serves a crucial role in SHH signaling to mediate the development of cancers." (PMID 39881254, 2025). "Targeting these cancer stem cells efficiently requires combining SHH signaling inhibitors with chemotherapy, radiation treatment, or immunotherapy." (PMID 39900571, 2025). "RNA-seq analysis showed that after TM treatment, there was an obvious decrease in the transcription levels of GLI2, a transcriptional factor, that regulates the cancer cell proliferation and apoptosis in the SHH signaling pathway." (PMID 39881254, 2025). "Furthermore, the inhibition of the SHH pathway by curcumin-containing treatments is linked to caspase-3 activation, a marker of apoptosis, indicating that curcumin not only disrupts survival signaling but also actively promotes programmed cell death, a desirable outcome in cancer therapy." (PMID 40227413, 2025). "In summary, the SHH signaling pathway is not only essential for CNS development but also plays a universal role in the progression of various cancers." (PMID 39900571, 2025). "The Sonic Hedgehog (SHH) pathwayplays an essential role in self-renewal, cell growth, drug resistance,metastasis, and recurrence of cancer stem cells (CSCs)." (PMID 38985013, 2024).
cancer (continued). "The main pathway and genes involved in cancer stem cells include the SHH/GLI-1 signaling pathway, IL6/JAK2/STAT 3 signaling pathway, GLI-1, GLI-3." (PMID 38730691, 2024). "The SHH signaling pathway also contributes to recurrence, metastasis, modulation of the cancer microenvironment, and sustaining cancer stem cells." (PMID 38730691, 2024). "Next, we identified a panel of 37 genes specifically activated by AR-V7 in EMT pathways, including SOX9 and SHH, the latter of which is also known to promote cancer metastasis." (PMID 38687617, 2024). "These developments underscore the complexity and potential of SHH pathway inhibition in treating a spectrum of cancers, necessitating continued research into optimise therapeutic outcomes." (PMID 39568072, 2024). "Abundant α‐SMA‐positive CAFs are located near SHH‐expressing cancer cells, particularly in invasive cancer,[19a] suggesting that CAFs assist cancer cell invasion upon recruitment by SHH signaling." (PMID 38976559, 2024). "Sonic Hedgehog (SHH) is a driver of embryonic patterning that, when corrupted, triggers developmental disorders and cancers." (PMID 38856684, 2024). "SHH signaling occurs in a paracrine mechanism in which hedgehog ligands produced by cancer cells bind to CAF receptors (such as Smoothened)." (PMID 38167055, 2024). "Our findings identify SALL4 as a CRL3REN substrate and a promising therapeutic target in SHH-dependent cancers." (PMID 38062245, 2024). "Given the increasing importance of targeted therapies in EC management, the SHH pathway’s exploration in this cancer type holds promise for enhancing our understanding of its molecular complexity and clinical implications." (PMID 39408773, 2024). "Some of these genes are reported in other cancer-implicated signaling pathways such as Ras (SPON1), SHH (SMO), and Notch (HEY2)." (PMID 39620202, 2024). "These compounds exhibit promising preclinical efficacy in SHH pathway-driven cancers, highlighting ongoing efforts to refine therapeutic strategies." (PMID 39568072, 2024). "Our scRNA sequencing analysis demonstrated a positive correlation between the expression of PARD3 and CD133 in the cancer stem cell lineage with highly activated SHH signalling." (PMID 38317186, 2024). "The Hh pathway has served as a promising therapeutic target for various cancers, with SHH, SMO, and GLI validated as targetable factors." (PMID 38909089, 2024). "Accordingly, a comprehensive understanding and targeting of CXCL12/CXCR4/NF-κB/SHH signaling holds great importance in treating cancer." (PMID 38004606, 2023). "While SHH activity typically remains dormant in mature adults, aberrations in the SHH pathway can reawaken its influence, promoting cancer initiation and progression." (PMID 38455361, 2023). "Depletion of cellular cholesterol with methyl-β-cyclodextrin inhibits SHH signaling, suggesting that lowering the level of cholesterol promotes anti-cancer effects." (PMID 37006607, 2023). "Uncontrolled activation of the SHH pathway has been found as a potential oncogenic driver signal promoting the proliferation of cancers." (PMID 37101292, 2023). "The SHH and its role in the anti-proliferative properties of AgNPs in this type of cancer was assessed as well as the potential mechanism of action of such NPs in comparison to Robotnikinin (a selective inhibitor of the SHH pathway)." (PMID 37407723, 2023). "Recently, the SHh pathway was found to possess a key function in the progression and metastasis of various cancers." (PMID 37533228, 2023). "Certain hints have emerged about regulation of SHH/GLI by bufalin in cancer inhibition but these aspects need to be tested comprehensively in animal model studies." (PMID 36903477, 2023). "The SHH and Notch signaling pathways play major roles in cancer development, and so are themselves a possible therapeutic target." (PMID 36797277, 2023).
cancer (continued). "Suforaphane targets cancer stem cells through modulation of nuclear factor kappa B (NF-κB), Sonic hedgehog (SHH), epithelial–mesenchymal transition, and Wnt/β-catenin pathways." (PMID 37836558, 2023). "Both SMO and the GLI family of zinc finger transcription factors in the SHH signaling pathway are regarded as important targets for cancer therapy." (PMID 37173787, 2023). "In Gorlin syndrome with dominant negative mutations of PTCH1, constitutive activation of SMO triggers the misregulation of SHH-mediated gene expression to contribute to the cancer disposition." (PMID 37006607, 2023). "Among dogs with malignant tumours, SHH and GLI-1 expression was significantly higher in metastatic patients (p = 0.01 and 0.007, respectively)." (PMID 37932728, 2023). "The strong expression of SHH was observed in carcinoma cells of the G1 stage with a diffuse staining pattern (>50% of neoplastic cells)." (PMID 37240278, 2023). "To discover global SHH-dependent gene expression patterns in cancer, we first determined differentially expressed transcripts in RNA sequencing data by comparing SHH MB (n = 58) to non SHH MB subgroup samples (n = 164) (Platform, R241)." (PMID 35831316, 2022). "SHH is known to upregulate several types of BMPs including BMP4 and can be produced by cancer-associated fibroblasts in the cancer microenvironment." (PMID 35902550, 2022). "In bladder and colorectal cancer, stromal cells were reported to maintain cancer cell differentiation through SHH-mediated BMP secretion." (PMID 36010986, 2022). "Treatment of cancer cells with the recombinant SHH protein promoted cell proliferation, but blocking SHH signaling with cyclopamine inhibited cancer cell proliferation." (PMID 35285760, 2022). "Currently, there are two FDA-approved SHH/Smoothened (SMO) inhibitors (SMOi: vismodegib and sonidegib) for treating BCCs and other cancer types in which SHH pathway activity is elevated." (PMID 36688010, 2022). "Targeting the SHH signaling pathway seems to provide a highly innovative therapeutic option for a broad variety of cancers." (PMID 35831316, 2022). "High SHH expression in in vitro conditions positively correlated with cancer cell proliferation, also canonical signaling promoted metastases development through neo-angiogenesis promotion." (PMID 36294994, 2022). "Bone microenvironment plays important role in PCa bone metastasis progression, especially the interaction between bone stromal cells and cancer cells, and we focus on the SHH-RANKL-IL6 signaling network between them." (PMID 35285760, 2022). "Among these pathways, Sonic Hedgehog (SHH) signaling is aberrantly activated in several human cancer entities." (PMID 35831316, 2022). "It has been reported that SHH increases cancer stemness, and accordingly, we next examined the expression of genes related to cancer stemness in LA-treated CT26 cells." (PMID 35047127, 2022). "SHH binds to the PTCH1 receptor expressed on the cell membrane of osteoblasts and cancer cells, to activate the SHH/PTCH1/GLI1 signaling pathway, which leads to the binding of GLI1 to the promoter of IL-6 and increases the IL-6 expression." (PMID 35285760, 2022). "The SHH pathway is also activated in multiple types of tumors, where it affects cancer cell proliferation, growth, and survival." (PMID 35163043, 2022). "Pathogenic germline mutations in known cancer predisposition genes have an important role, mainly in WNT-activated and SHH-activated MB." (PMID 36497448, 2022). "Based on these studies, inhibitors that alter the catalytic action of SHH-regulating enzymes are presently being investigated as potential drugs for SHH-driven cancers, including MB." (PMID 35573667, 2022). "IHC analysis of the TMA containing a PDX of the ISO76A cell line revealed that subsets of cancer cells within the PDX express SHH." (PMID 35902550, 2022). "Long non-coding RNAs (lncRNAs) can contribute to cancers that are driven by Sonic hedgehog (SHH) signaling." (PMID 35831316, 2022).
cancer (continued). "In adult, SHH acts as an oncogene to transform adult stem cells to cancer stem cells and is involved in tumorigenesis of many types of cancer." (PMID 34646822, 2021). "Recently, several studies have indicated that the SHH signaling pathway regulates autophagy in human cancers, and such interactions exhibit distinct pathological or pharmacological roles." (PMID 34076346, 2021). "Recent clinical studies demonstrated that targeting SHH signaling pathway is beneficial for various types of human cancers." (PMID 34076346, 2021). "In the present study, we investigated how oncogenic NKX6-1 confers poor prognosis in LMS and how NKX6-1 regulates cancer stem cells through activation of the SHH and NOTCH pathways." (PMID 33906647, 2021). "The induction of sonic hedgehog (SHH) by KRAS in cancer cells triggers the expression of the transcription factor GLI1 in fibroblasts." (PMID 33691728, 2021). "Regarding SHH signalling, current drug development efforts are focused on inhibiting aberrant SHH/HH pathway activation in cancer." (PMID 34576017, 2021). "SHH pathway is highly activated in pancreatic CSCs and plays an essential role in cancer initiation, progression, and metastasis." (PMID 33494284, 2021). "Our data show that MAPK15 knock-down reduces canonical HH signaling and inhibits proliferation of SHH-driven MB cell lines and generation of cancer stem cells." (PMID 34638386, 2021). "Cancer-associated fibroblasts activation signaling relies on various stimuli from the TME, and SHH is one of these." (PMID 33614646, 2021). "Cilia in cancer cells harbor cell growth and drug resistance phenotypes through governing a myriad of signaling systems such as SHH, WNT, NOTCH, PDGF, and other receptor tyrosine kinases (such as IGF1R, FGFR)." (PMID 34831357, 2021). "Our results demonstrated that NKX6-1 acts through the sonic hedgehog (SHH) pathway to increase cell proliferation, drug resistance, and cancer stemness in vitro and tumorigenicity in vivo." (PMID 33906647, 2021). "Increasing evidence has reported the interaction between the SHH signaling pathway and autophagy in various types of cancer cells." (PMID 34076346, 2021). "Meanwhile, sulforaphane was reported to induce apoptosis of cancer cells through AMPK-dependent or SHH pathway." (PMID 34589134, 2021). "Previous work in mouse models has shown that GLI2 over-expression in the skin leads to the development of basal cell carcinoma (BCC), with sustained or aberrant upregulation of SHH/GLI cascade for cancer growth." (PMID 33494284, 2021). "Although large-scale studies are needed, our study demonstrated that NKX6-1 expression regulates the cancer stemness phenotype through activation of the SHH pathway and is correlated with poor prognosis in LMS." (PMID 33906647, 2021). "There are two models for the over-activation of the Hh pathway in cancer: (a) ligand-dependent model: tumors are able to over-activate SHh-GLI pathway via autocrine signaling to produce high level of SHh ligands." (PMID 34113570, 2021). "Many lines of evidence support the idea that SHH signaling is important in maintaining cancer stem cell in various cancers." (PMID 32962123, 2020). "In this context, the emerging role of Sonic hedgehog (SHH) signaling in cancer has been critically evaluated, focusing on the potential for targeting SHH signaling as an anticancer strategy." (PMID 33228057, 2020). "It activates SHH signaling and enhances cancer cell invasiveness of the ER-positive T47D (HER2−) and BT-474 (HER2+) cells." (PMID 32962123, 2020). "During the last years, it has been shown that the SHH/Gli signaling pathway is involved in many human cancers." (PMID 33228057, 2020). "Since HH signaling is involved in regulating cancer stem cell subtypes in several cancers, it is plausible that SHH regulates this subtype partially via GLI3 in a paracrine manner." (PMID 32245491, 2020).
cancer (continued). "In this model, transgenic expression of a constitutively active mutant isoform of GLI2 in keratinocytes activates SHH signaling and induces cancer lesions similar to human BCC." (PMID 31963474, 2020). "In this context, the role of the SHH signaling pathway in cancer has been evaluated, focusing on the potential for targeting the actors of this signaling pathway as an anti-cancer strategy." (PMID 33228057, 2020). "Three HH ligands (SHH, IHH and DHH) are involved in organ homeostasis and cell fate differentiation, and their expression are associated with cancer progression." (PMID 32962123, 2020). "Our findings can have clinical implications given recent advancements in therapeutic research in the miR-506-3p and SHH pathways in cancer treatment." (PMID 33291316, 2020). "Some investigators found that drug transport pump expression in cancer stem cells enabling cytotoxic drug resistance were upregulated by SHH signaling." (PMID 31979397, 2020). "The Sonic hedgehog (SHH) signaling pathway, strongly involved in the development of many cancers, regulate transcription via the transcriptional factors Gli1-3." (PMID 33228057, 2020). "At the molecular level, it has been shown that SHH signaling drives the progression of cancers by regulating cancer cell proliferation, malignancy, metastasis, and the expansion of CSCs." (PMID 32957513, 2020). "Inactivation of smoothened protein (SMO) by the antagonists in SHH-driven cancer types is essential for inhibition of cancer progression." (PMID 33083505, 2020). "SHH plays an important role in organogenesis, cancer, and the cancer microenvironment of some organs." (PMID 31979397, 2020). "In our study, we found that inhibiting the exosomal transfer of SHH from CAFs to cancer cells can influence the progression of ESCC in vivo and in vitro." (PMID 32030915, 2020). "Pharmacological inhibition of the sonic hedgehog (SHH) pathway can be beneficial against certain cancers but detrimental in others." (PMID 30645190, 2019). "Clinical trials have revealed varying success with SHH pathway-targeting drugs in different cancer types." (PMID 31401336, 2019). "Second, we demonstrated paracrine signaling in which the cancer parenchyma secretes SHH ligands that bind receptors on the surrounding stroma, thus activating stromal SHH signaling." (PMID 31744214, 2019). "Stimulation with SHH resulted in an up-regulation of cancer stemness in EC sphere cultures, as indicated by increased sphere formation after sorting for CD44+/CD24− EC cancer stem-like cell (CSC) population." (PMID 31200527, 2019). "SHH in the cancer stroma was strongly expressed in blood vessels, spindle cells, and round cells in ED type." (PMID 31744214, 2019). "The crosstalk between TGF-β and SHH pathways has also been reported in cancer, as well as in cyclosporine-enhanced cell proliferation in human gingival fibroblasts." (PMID 31202261, 2019). "Sonic hedgehog (SHH) and its signaling have been identified in several human cancers, and increased levels of SHH expression appear to correlate with cancer progression." (PMID 31744214, 2019). "GREM1, a member of antagonist family that has been shown to relay the sonic hedgehog (SHH) signal from the polarizing region to the apical ectodermal ridge during limb bud outgrowth in mouse, is involved progression of various cancers." (PMID 31043858, 2019). "Hypoxia has also been associated with the increased SUMOylation of multiple proteins, including GLI family proteins, which are key mediators of SHh signaling, and has become a promising target to develop drug-resistant drugs for cancer treatment." (PMID 31616295, 2019). "Oncogenic KRAS induces the expression of Sonic Hedgehog (SHH) in cancer cells, whilst SHH induces expression of the transcription factor GLI family zinc finger 1 (GLI1) in fibroblasts." (PMID 31847096, 2019).